STAT3 (signal transducer and activator of transcription 3)
Diseases named in the same sentence as STAT3 in open-access papers (continued):
Sharing a sentence is not in itself a finding about the gene and the disease.
tumor (continued). "However, the strong inhibition of tumor growth that we observed suggests that the STAT3 function in vivo is largely depended on NLRC5." (PMID 33754073, 2021). "STAT3 signaling is a major intrinsic pathway for cancer inflammation due to its frequent activation in malignant cells, with a key role in regulating numerous genes crucial in inflammation-induced cancer and the tumor microenvironment." (PMID 34443544, 2021). "In addition, inhibiting miR-216a-5p and activating the JAK2/STAT3 pathway can promote tumor cell spheroidization, up-regulating the levels of stem marker proteins CD90 and CD133." (PMID 34900727, 2021). "In general, STAT3 signalling promotes a tumour microenvironment that enables the tumour to proliferate and spread as well as avoid the immune system; within the tumour, STAT3 regulates pathways involved in cell proliferation, viability, angiogenesis and metastases." (PMID 33274592, 2021). "STAT3 is constitutively activated both in tumor cells and TICs." (PMID 34880206, 2021). "Considering that the increase of liver inflammation was accompanied with p‐STAT3 up‐regulation of tumour tissues for HCC patients, STAT3 inhibitor may improve the sorafenib efficacy for HCC patients with marked liver inflammation." (PMID 33410581, 2021). "It has been shown that ARMH4 can interact with and inhibit the function of mTOR complex 2 kinase activity and function as a tumor suppressor in hematological malignancies, which is driven by interleukin 6 (IL-6)–signal transducer and activator of transcription 3 (STAT3) signaling pathways." (PMID 34660292, 2021). "In addition, xenograft results have showed that DHTS suppressed tumor growth of SMMC7721 cells in vivo by inhibiting the p-STAT3." (PMID 33995073, 2021). "Here, we evaluate the countenance of T cell immunoglobulin and mucin-domain containing-3 (Tim-3), and various immunosuppressive factors within tumor-infiltrated Treg cells after treatment with anti-PD-1 or the indicator transduction and activator of transcription 3 (STAT3) inhibitors." (PMID 33936081, 2021). "It has been proved that IL-22 may directly promote tumor growth by engaging STAT3 signaling in tumor cells." (PMID 34941188, 2021). "The STAT3 signaling pathway plays a vital role in tumor growth." (PMID 35154340, 2021). "However, the associations were not absolute: some patients had few infiltrations of TANs and/or TAMs, while exhibited strong tumor p-STAT3 density; some other patients displayed weak tumor p-STAT3 density, although infiltrated by abundant TANs and/or TAMs." (PMID 33692217, 2021). "Indeed, it has been reported that grapefruit-derived nanoparticles loaded with a STAT3 inhibitor inactivate STAT3 in GL26 tumor cells and improve survival rates of mice." (PMID 34959929, 2021). "JMJD3 regulation by STAT3 was found in tumor samples from different patients." (PMID 33478063, 2021). "These preclinical results underscore therapeutic potential and priority in targeting STAT3 activity in tumor-associated immune cells rather than in cancer cells alone." (PMID 34067832, 2021). "The forward signalling cascades and reverse feedback loop between NEAT1 and STAT3 have been verified in different tumours, and some tissue-specific or universal miRNAs will fill in the gap and form one tissue/tumour-specific NEAT1/miRNA/STAT3 axis for the indicated tumour." (PMID 33546665, 2021). "IL‐10 could bind with IL‐10 receptors on tumor cells to activate STAT3, which thus promotes the proliferation of tumor cells via the activation of cell cycle‐related proteins." (PMID 34026610, 2021). "Furthermore, IL-6 activation of the JAK/STAT3 pathway induces tumor cell survival by up-regulation/activation of anti-apoptotic proteins MCL-1 and BCL-XL, and c-MYC." (PMID 34067236, 2021). "STAT3 signaling pathway is known to play crucial roles in tumor cells survival, and proliferation." (PMID 34663387, 2021).
tumor (continued). "In addition, STAT3 regulates the activity and proliferation of T cells and the function of dendritic cells to participate in tumour immunity." (PMID 34425834, 2021). "Treatment with SeS2 also decreased p‐C‐MET and p‐STAT3 expression in SMMC‐7721 tumor tissues." (PMID 34586726, 2021). "This could inform therapeutic strategies for combining adoptive NK cell transfer and IL-15 administration with targeting of STAT3 in cancer and attenuating the known interference of STAT3 inhibition with NK cell anti-tumor activity." (PMID 33782423, 2021). "MiR-155 also activated STAT3 signaling and promoted tumor progression in breast cancer." (PMID 33918136, 2021). "Results illustrated that STAT3 may be influenced during the tumorigenesis process of lung GGO as it is expressed higher in the tumor tissues than in normal lung tissues, while the trend of JAK1 seems to be consistent with that of IL-6." (PMID 34568032, 2021). "STAT3 is a member of the signal transduction and activator of transcription family mediating tumor proliferation, progression, metastasis, and immunity in the tumor microenvironment." (PMID 33936081, 2021). "Here we show that interaction with tumor microenvironment elements, mainly activated monocytes through IL-6 secretion, and the extracellular matrix protein fibronectin, induces the Stat3 transcriptional pathway and upregulates ODZ1 which results in GBM cell migration." (PMID 34376733, 2021). "STAT3 plays an important role in wound healing and tissue repair and it is frequently overactivated in malignant tumors, resulting in inflammation-driven repair, promotion of drug resistance and tumor progression." (PMID 34830209, 2021). "Moreover, silencing of TRAF6 remarkably decreased the levels of phosphorylated STAT3 in MDSCs from tumor tissue of TB mice." (PMID 33717204, 2021). "Likewise, the activation of STAT3 signaling in tumor-implant models significantly decreased the expression of tumor-secretory proinflammatory mediators." (PMID 34829795, 2021). "IL-10 exerts regulatory effects on inflammatory pathways involving STAT3 and NF-κB, which may influence tumour progression." (PMID 34944729, 2021). "The signal transducer and activator of transcription factor 3 (STAT3) signalling pathway is upregulated in TAMs and is responsible for the production of tumor-promoting inflammatory molecules, such as IL-10 and IL-6, as well as inhibition of the tumor-suppressive inflammatory molecule TNF." (PMID 33766119, 2021). "Additionally, IL-6 binds to its receptor IL-6R to regulating Janus kinase (JAK)/STAT3 signaling pathways, then stimulating the proliferation of tumor cells and the stemness of breast cancer stem cells (CSCs)." (PMID 33413697, 2021). "We found RBPJ to be a direct target gene of signaling active STAT3, which may explain these observations together with the tumor cell-autonomous processing of NOTCH leading to NICD production and the assembly of the transcriptionally active RBPJ/NICD complex." (PMID 33530306, 2021). "In addition, IL-6 released by TAMs, in turn, would further activate the STAT3 pathway, forming a positive feedback loop between tumor and TME cells." (PMID 34638305, 2021). "For example, aberrant EGFR signaling in NSCLC cells upregulates PDL1 expression through activation of the IL6/JAK/STAT3 pathway, while combined STAT3 and PDL1 inhibition renders tumor cells more susceptible to cytotoxic T-cell mediated killing and delays tumor growth in mice." (PMID 34944848, 2021). "In nude mice tumor tissue, p-Stat3 was under-expressed in the circADARB1 knockdown group." (PMID 34736477, 2021).
tumor (continued). "Indeed, the secretion of pro-inflammatory cytokines IL-6, IL-11, TNFα, and IL-1β enhances tumor cell proliferation through the signal transducer and activator of transcription 3 (STAT3) and the anti-apoptotic nuclear factor κB (NF-κB)." (PMID 34680425, 2021). "We observed that STAT3 loss in B cells did not affect tumor incidence, severity, differentiation, or overall survival of Eμ-myc mice." (PMID 33651821, 2021). "Micellar formulations were able to deliver cucurbitacin to tumor cells and inhibit STAT3." (PMID 33525658, 2021). "Additionally, IL-6 induces the production and maintenance of BC stem cells through the activation of nuclear factor kappa-light-chain-enhancer of activated B cells (NF-kB) and STAT3, thereby promoting tumor progression." (PMID 34638283, 2021). "STAT3 is crucial for tumor development and as a target for anti-tumor therapy." (PMID 34633989, 2021). "Taken together, our in vitro and in vivo experiments showed that inhibition of STAT3 activity might be critical for fraxetin-mediated anti-tumor effects in PDA." (PMID 34320467, 2021). "MiR-223 is another tumor suppressor which targets the STAT3 factor, similar to miR-125." (PMID 33430952, 2021). "Potentially, STAT3 inhibition by itself might already reduce the inhibitory effect of the PD-1/PD-L1 axis, especially when tumor PD-L1 expression is regulated through oncogenic pathway activation often seen in HPV− HNSCC." (PMID 35047999, 2021). "Interestingly, STAT3 has been also suggested to be a malignancy factor in CTCL due to its potential to inhibit tumor cells apoptosis." (PMID 32270320, 2021). "Collectively, STAT3 reactivation by colivelin reverses the anti-tumor effects of fraxetin on PDA." (PMID 34320467, 2021). "Furthermore, inhibiting STAT3 decreased miR‐27b‐3p levels in mesenchymal tumour cell‐derived exosomes." (PMID 34936736, 2021). "More importantly, we verified through cell experiments that LTF overexpression mediates JAK/STAT pathway to inhibit STAT3 expression and reduce tumor-derived GM-CSF secretion, regulate tumor immune microenvironment, and inhibit tumor cell proliferation and migration." (PMID 34868909, 2021). "The role of STAT3 in CSC has been described in various tumor types including OC." (PMID 34645505, 2021). "Acetyl-bufalin can exert anti-tumour effect by inhibiting the CDK9/STAT3 signalling pathway." (PMID 33122847, 2021). "These evidence supported a crucial role of STAT3 in fraxetin-mediated anti-tumor effects again." (PMID 34320467, 2021). "In addition, STAT3 is activated constitutively in a majority of malignant tumours with high invasiveness and autophagy levels, suggesting that STAT3 works as an oncogene." (PMID 34645519, 2021). "TAMs secreting IL-6, activating IL-6R/STAT3/miR-204-5p pathway of tumor cells." (PMID 34095111, 2021). "IL-6 is a potent stimulator of STAT3 signaling in the tumor microenvironment." (PMID 34771643, 2021). "STAT3 plays a vital role in the occurrence and development of tumours." (PMID 33259114, 2021). "Tumor volume from mice of the two experiment groups (STAT3-NC + AETW, STAT3-OE + AETW)." (PMID 34867344, 2021). "The most recent studies suggested that NTZ may be used as a novel STAT3 pathway inhibitor for the treatment of neoplastic diseases." (PMID 34955850, 2021). "There are multiple reports of anti-inflammatory and antioxidant effects of capillarisin, which has also been shown to inhibit tumor cell invasion, inhibit signaling transducer and activator of transcription 3 (STAT3) activation, slow cell growth, and promote apoptosis in various cancer cell lines." (PMID 35211087, 2021). "Importantly, STAT3 blockade repressed V-ATPase expression, sensitized tumor cells to anoikis, increased ROS production, and misfolded protein accumulation while STAT3 overexpression upregulated V-ATPase and promoted anoikis resistance." (PMID 34234852, 2021).
tumor (continued). "Moreover, OSMR expression in stellate cells is required for co-culture dependent activation of phospho-STAT3 signalling in tumour cells." (PMID 34921158, 2021). "A derivative of bufalin has been reported to play an anti-tumour role by inhibiting the STAT3 pathway;26 thus, we thought that acetyl-bufalin may affect STAT3 phosphorylation (P-STAT3)." (PMID 33122847, 2021). "Furthermore, activation of STAT3 is associated with MDSC activation in CRC and its phosphorylation is correlated with tumor growth." (PMID 34381456, 2021). "One possible explanation is that Ob-R overexpression in tumor cells might activate the leptin-Ob-R-JAK2/STAT3 axis as well as other pathways such as PI3K/AKT and MAPK producing a proliferative stage through which is more sensitive to chemotherapy." (PMID 34210055, 2021). "It has been shown that STAT-3 is constitutively expressed in various immune cells in the tumor microenvironment, and knocking out STAT-3 in tumor-infiltrating immune cells generates an intrinsic immune-surveillance system that prevents cancer cell proliferation and metastasis." (PMID 33987190, 2021). "Furthermore, wogonin was also reported to inhibit tumor growth and enhance immune system activation by suppressing STAT3 signaling." (PMID 33558586, 2021). "Furthermore, tumor cell-produced cytokines have been shown to induce higher levels of STAT3 phosphorylation in infiltrating immune cells while suppressing immune cell activity." (PMID 34759824, 2021). "It is hard to deny the potential impact of STAT3 downregulation on tumor angiogenesis inhibition." (PMID 33936081, 2021). "Reactivation of STAT3 reverses the anti-tumor effects of fraxetin." (PMID 34320467, 2021). "With reduced IL‐1β activity, there is less tumor-derived IL-1β and IL-6 activity on bone marrow cells and ultimately decreased STAT3 activity in this cell population, supporting our previous findings that tumor-NLRP3 activity induces IL-1β and IL-6 in the bone marrow." (PMID 34531850, 2021). "Collectively, these findings suggest a role for tumor cell-intrinsic and -extrinsic STAT3 signaling in regulating anti-tumor immunity via expression of checkpoint molecules and represent a promising strategy to improve the efficacy of immune checkpoint inhibitors." (PMID 34944848, 2021). "Indeed, STAT3 acts as the upstream introducer of apoptosis in many types of cells, and the STAT3 inhibitor has been widely used in the field of anti-tumor treatment via suppressing apoptosis." (PMID 34938738, 2021). "Hence, targeting STAT3 in the tumor microenvironment allows for tumor shrinkage due to proper immune system re-activation." (PMID 34067832, 2021). "Several signaling pathways in tumor cells, including Akt, mTOR, STAT3, and Notch, may be responsible for the altered tumor environment exposed to tumor therapies." (PMID 33732706, 2021). "Considering that both IL‐6 and IL‐27 contribute to tumour progression through JAK/STAT3 signalling pathway, we next elucidated whether CD63 regulated the activation of signal transducer and activator of transcription‐3 (STAT3) by Western blot analysis." (PMID 33277798, 2021). "Moreover, signal transducer and activator of transcription 3 (STAT3) overexpression, autophagy induction, and the interaction of immune cells and cancer stem cells that support the tumor microenvironment lead to GEM resistance, relapse, and death." (PMID 34771150, 2021). "Moreover, the phosphorylation, as well as activation of ERK1/2, PRAS40, STAT3 and mTOR, which are well-documented signaling pathways playing important role in apoptosis resistance and tumor progression, was significantly alleviated in shPOLQ cells." (PMID 34517891, 2021). "Furthermore, STAT3 signaling is correlated with a decrease in effector T cells infiltration of the tumor and prevents CD8+ T cell activation by increasing the secretion of INF-γ." (PMID 34440802, 2021).
tumor (continued). "Different previous studies showed that NEN and niclosamide exert inhibitory effects on tumor growth, which was proposed to be mediated through inhibition of Stat3 transcription factor activity as well as probably indirect negative effects on mTORC1 and Wnt signaling." (PMID 33665961, 2021). "It was also reported that the TME activates STAT3 signalling in human umbilical vein endothelial cells, and that the tumour microenvironment may affect angiogenesis through the STAT3 signalling pathway." (PMID 34496870, 2021). "Conversely, IL6 blockade inhibited epithelial STAT3 activation and tumor growth in mice." (PMID 34944848, 2021). "Targeting an immunosuppressive tumor microenvironment by STAT3 inhibition may consequently enhance the efficacy of immunotherapy." (PMID 33786638, 2021). "Hence, according to molecular signaling, nobiletin inhibits tumor progression by inhibiting the EGFR/JAK2/STAT3 pathway and PD-L1 expression in NSCLC cells." (PMID 34576006, 2021). "In contrast to PO-acet.-STAT3 peptide, PS-acet.-STAT3 exhibited high cell permeability and significant inhibitory effects on cell proliferation and gene expression of STAT3 target genes in patient primary tumor spheres." (PMID 33491667, 2021). "In addition, silencing the expression of AR in PCa cells by RNA interference, it was found that AR knockdown resulted in more powerful STAT3 activation, thereby compensating for the silenced AR and promoting tumor growth." (PMID 33995485, 2021). "When tumor factors were removed or STAT3 was inihibited, the ImC generation was reversed." (PMID 33919157, 2021). "Interestingly, STAT3 in endothelial cells was activated only at the tumour site, while it was rarely activated in normal liver tissues." (PMID 34496870, 2021). "MSI1 may regulate GBM radioresistance, CSCs and tumor motility through miR-671-5p inhibition to increasing STAT3 and TRAF2 presentation." (PMID 35052701, 2021). "Although STAT3 signaling in tumor-associated immune cells is known to play a critical role in suppressing antitumor immune responses, few studies have analyzed STAT3 activity in tumor-surrounding lymphocytes in patient tumors before and after specific treatments." (PMID 34956861, 2021). "Moreover, one-time PARPi treatment activated STAT3 both in tumor cells as well as diverse immune subsets and fibroblasts." (PMID 34956861, 2021). "STAT3 is frequently activated in NSCLC, has been linked to macrophage polarization balance and has a pivotal role in driving tumor-promoting inflammation and the evasion of anti-tumor immunity." (PMID 34440757, 2021). "LC-C may promote radiation induced anti-tumor effect by increasing the expressions of ERRFI1 and associated with EGFR and STAT3 signaling pathways." (PMID 33869036, 2021). "M2-like macrophages have been reported to upregulate the expression of the glucose-regulated protein of 78 kDa (GRP78) in tumor cells, promoting STAT3 phosphorylation, leading to the downstream inflammatory factors including IL-1β and TNF-α upregulation, which facilitates tumor progression." (PMID 34326840, 2021). "Knockdown of STAT3 using siRNA inhibits the growth of tumor cells and induces apoptosis." (PMID 34090412, 2021). "In addition to direct inhibition of effector cells, Bregs with activated STAT3 are found in proximity to tumor vasculature and proved to be proangiogenic and positively correlated with tumor progression." (PMID 33868318, 2021). "However, STAT3 is known to be activated in many types of immune cells in the tumor microenvironment." (PMID 33491667, 2021). "STAT3 is considered an oncogene and is highly expressed in a variety of tumor tissues and cells." (PMID 33462379, 2021).